ATAT1 (alpha tubulin acetyltransferase 1)
Diseases named in the same sentence as ATAT1 in open-access papers:
ATAT1 is named in the same sentence as 23 diseases in open-access papers, as found by Europe PMC text mining. Sharing a sentence is not in itself a finding about the gene and the disease. The quoted sentences say what the papers report.
breast carcinoma (7 papers, 2016 to 2024). "Endogenous Ac-Tu level has recently been linked to metastatic behavior in breast cancer, therefore differentiating the role of αTAT1 in more types of cancer and its potential role as therapeutic target are worthy of further consideration." (PMID 27551500, 2016). "Despite recent evidence which points to ATAT1 and K40 tubulin acetylation as significant players in several types of cancer, in particular breast cancer, little is known about the underlying mechanisms and the relevance of ATAT1 acetyltransferase activity in the cancer process." (PMID 38652325, 2024). "Moreover, ATAT1 and ER stress marker genes may be useful diagnostic markers in various breast cancer types." (PMID 34199510, 2021). "In breast cancer, tubulin acetylation and ATAT1 have been found to regulate cell protrusions, adhesion and invasion, key steps of tumour dissemination." (PMID 38652325, 2024). "In another breast cancer study, ATAT1 catalyses MT acetylation at the membrane-associated clathrin-coated pits through its interaction with the clathrin adaptor AP2 and ATAT1/AP2 interaction is required for directional migration." (PMID 38652325, 2024). "The presence of αTAT1 is needed for extracellular matrix invasion of the highly metastatic MDA-MB-231 breast cancer cell line." (PMID 37106761, 2023). "Knockdown of ATAT1 induced ER stress and inhibited breast cancer cell progression, including migration, invasion, proliferation, and spheroid formation, via downregulation of gene expression related to cancer-related pathways." (PMID 34199510, 2021). "A balance of acetylation and deaceylation by ATAT1/HDAC6 enzymes regulates breast cancer cell migration and invasion." (PMID 27902487, 2017). "In breast cancer cells, ATAT1 binds and regulates cortactin acetylation levels and colocalizes with cortactin at the adherent surface of the cells." (PMID 27322556, 2016). "ATAT1 is required for 2D migration and invasive capability of breast cancer cells in collagen matrix." (PMID 27322556, 2016). "Ectopic ATAT1 expression in cultured cells also increases tubulin acetylation and enhances formation of microtentacles, which are membrane protrusions in detached breast cancer cells." (PMID 27322556, 2016). "Moreover, analysis of ATAT1 transcripts in breast cancer databases has shown that ATAT1 is upregulated in most cancer tissues when compared to the normal tissues." (PMID 38652325, 2024). "Overall, these studies suggest that ATAT1 may be considered an important molecular marker of invasion and progression in breast cancer." (PMID 38652325, 2024). "In addition, breast cancer patients with high expression of ATAT1 and MAPK8, RASSF1, BCL2, CXCL8, and FGF1, had a poor prognosis." (PMID 34199510, 2021). "Finally, the expression of ATAT1 and ER stress marker genes were negatively correlated in various breast cancer types." (PMID 34199510, 2021). "αTAT1 overexpression, which leads to higher α-tubulin acetylation levels, increases the formation of microtentacles and reattachment in a non-metastatic breast cancer cell line and inhibits cancer cell migratory and invasive ability and tumour metastasis on an orthotopic lung cancer animal model." (PMID 37106761, 2023).
colon cancer (7 papers, 2019 to 2024). "Genetic ablation of α-tubulin acetyltransferase, αTAT1, suppresses colon cancer proliferation and invasion." (PMID 36394953, 2023). "In colon cancer, it was also reported that the increased expression of αTAT1 contributed to the cancer cell invasion." (PMID 34508164, 2022). "Microtubule hyperacetylation has been shown to have carcinogenesis promotive effects and ATAT1 transcript levels have been reported to be increased in human colon cancer tissues." (PMID 34502304, 2021). "In colon cancer, ATAT1 downregulation inhibits cell proliferation and cell invasion through modulation of Wnt1/β-catenin signaling." (PMID 32498717, 2020). "However, the ATAT1 activity is required for microtubule organization, it is specifically upregulated in colon cancer tissue and LDHA has an aberrantly high expression in multiple cancers." (PMID 31540229, 2019).
lung carcinoma (4 papers, 2018 to 2024). "On the other hand, decreased tubulin acetylation by αTAT1 RNA interference downregulated Mcl-1 expression in patient-derived primary lung cancer and paclitaxel-resistant lung cancer cells." (PMID 33824297, 2021). "In lung cancer, ATAT1 plays a key role in cell migration and invasion through the modulation of epithelial–mesenchymal transition and cell polarity." (PMID 32498717, 2020). "Our results indicate that the anti-migratory effects of CPTH6 on lung cancer cells are dependent of its effect on α-tubulin acetylation, thus suggesting that this compound may also inhibit ATAT1, in addition to GNC5 and pCAF." (PMID 32498717, 2020). "While one study showed that ATAT1 silencing did not impact paclitaxel cytotoxicity in colon cancer cells, a correlation between high tubulin acetylation levels and paclitaxel resistance was observed in patient-derived lung cancer cells and in paclitaxel-resistant lung cell lines." (PMID 38652325, 2024).
Anxiety (2 papers, 2023). Intense feelings of nervousness, tension, or panic often arise in response to interpersonal stresses. "Among them, 63 protein-coding genes, including Atat1 and Pfn2 known to be associated with anxiety-related or exploration behavior in mice, respectively, were located surrounding the identified candidate polymorphisms." (PMID 37147374, 2023). "When considering NPDs of interest, depression, and anxiety alone, the strongest pleiotropic effects of single genes, i.e. highest number of associations with disorders, were observed for PFN2, HTRA1, SCRN1, ATAT1, and SYN3." (PMID 37461513, 2023).
silicosis (2 papers, 2016 to 2024). Silicosis is a respiratory disease caused by breathing in (inhaling) silica dust. "In a rat model of lung silicosis, a fibrotic condition resulting in cell stiffening, a reduced expression of ATAT1 was observed in silicosis nodules or interstitial fibrotic regions along with an increased fibroblast-to-myofibroblast differentiation." (PMID 38652325, 2024).
breast tumours (1 paper, 2024). "In the last years, many studies have highlighted the involvement of ATAT1 functions in breast tumours, while ATAT1 role in other tumours remains still elusive." (PMID 38652325, 2024).
HIV-1 infection (1 paper, 2025). The type species of lentivirus and the etiologic agent of acquired immunodeficiency syndrome (AIDS). "Rather, we observe that inhibiting microtubule acetylation by CRISPR-mediated knockout of αTAT1 led to a modest but significant increase in HIV-1 infection." (PMID 39804091, 2025). "As expected, we observed that αTAT1 knockout prevented microtubule acetylation induced by HIV-1 infection." (PMID 39804091, 2025). "We also examined the ability of TRIM69 to inhibit HIV-1 infection in the context of αTAT1 knockout." (PMID 39804091, 2025). "However, we found that TRIM69 was able to potently restrict HIV-1 infection even when microtubule acetylation was prevented by αTAT1 KO." (PMID 39804091, 2025). "Furthermore, we observed that αTAT1 knockout resulted in reduced levels of stable microtubules following HIV-1 infection, consistent with the role of microtubule acetylation as a key post-translational modification needed to increase microtubule resistance to depolymerization." (PMID 39804091, 2025). "In contrast, HIV-1 infection did not induce further changes in these tubulin modifications compared with the uninfected aTAT1 KO cell line (left)." (PMID 39804091, 2025). "Upon HIV-1 infection, cells lacking αTAT1 exhibited approximately a twofold increase in HIV-1 infection compared with control cells." (PMID 39804091, 2025). "To further examine microtubule stability in the absence of acetylation during HIV-1 infection, we treated both wild-type and αTAT1 KO THP-1 cells with 0.1 μM nocodazole 5 h post-infection." (PMID 39804091, 2025). "A different result was observed in THP-1 cells, as neither αTAT1 KO nor HIV-1 infection significantly altered these post-translational modifications individually or in combination (right)." (PMID 39804091, 2025). "In CHME3 microglial cells, αTAT1 knockout resulted in an increase in detyrosinated tubulin when compared with wild-type cells in the absence of HIV-1 infection (WT) (left)." (PMID 39804091, 2025). "While we observed no direct change in both polyglutamylation or detyrosination of α-tubulin following αTAT1 knockout and HIV-1 infection, our study did not specifically perturb these pathways to assess their role in HIV-1 infection or TRIM69 restriction." (PMID 39804091, 2025). "However, we observed that αTAT1 knockout did not negatively influence HIV-1 infection, and instead led to an increase in HIV-1 infection." (PMID 39804091, 2025). "To more definitively understand the role of microtubule acetylation on HIV-1 infection and in TRIM69-mediated HIV-1 restriction, we examined both HIV-1 infection and TRIM69-mediated restriction of HIV-1 in cells lacking αTAT1, the acetyltransferase responsible for microtubule acetylation." (PMID 39804091, 2025).
injury (1 paper, 2018). Damage inflicted on the body as the direct or indirect result of an external force, with or without disruption of structural continuity. "Studies are under way to explore the spatio-temporal relationship between these two opposing enzymes in regulating axonal growth, as are studies to define the role of αTAT1 in vivo, especially in animal models of traumatic brain injury and spinal cord injury." (PMID 29497702, 2018).
prostate carcinoma (1 paper, 2021). A carcinoma that arises from epithelial cells of the prostate gland. "Nine novel candidate drivers were identified in prostate cancer of Sardinia, including mutations in the SDC1 protein (R277S) and the ATAT1 protein (D19V) observed in two of the samples for each protein." (PMID 33391440, 2021).
cancer (11 papers, 2016 to 2024). A tumor composed of atypical neoplastic, often pleomorphic cells that invade other tissues. "Notably, despite recent evidence which points to ATAT-1 as a significant player in several types of cancer, little is known about the underlying mechanisms and the relevance of ATAT1 acetyltransferase activity on cancer." (PMID 35008169, 2021). "A set of genes involved in cancer progression, especially focal adhesion genes, were downregulated in both ATAT1-knockout and tunicamycin-treated cells, whereas ATAT1 overexpression restored the gene expression inhibited by tunicamycin." (PMID 34199510, 2021). "The ATAT1 transcript was increased in most cancer tissues when compared to the levels in normal tissues." (PMID 34199510, 2021). "Some recent studies have reported that acetylation of tubulin by ATAT1 can affect various pathways, such as cell motility and mitosis, which in turn impinge on cancer cell proliferation, adhesion, invasion, and metastasis." (PMID 35008169, 2021). "Conversely, the role of ATAT1 in cancer is greatly understudied, as compared with the role of this acetyltransferase in development and non-cancer diseases." (PMID 35008169, 2021). "Recent reports suggest that ATAT1 plays a prominent role in many cellular processes related to cancer dissemination, including cell adhesion, migration and invasion." (PMID 27322556, 2016). "In cells grown on a stiff matrix, ATAT1 silencing induces ER stress and inhibits cell migration, invasion, proliferation, and spheroid formation, via downregulation of gene expression related to cancer-related pathways." (PMID 38652325, 2024). "Given that acetylated MTs are intimately involved in multiple cell activities, ATAT1 function may have an impact on organismal physiology and in several diseases, including neurodegeneration and cancer." (PMID 38652325, 2024). "Recent evidence has shed light on the role of ATAT1 and K40 tubulin acetylation in the global reorganization of organelle intracellular positioning that occurs following centrosome amplification, a condition commonly observed in cancer." (PMID 38652325, 2024). "The migration of cancer cells is affected by αTAT1, as well." (PMID 37106761, 2023). "Downregulation of microtubule acetylation using shRNA or CRSIPR/Cas9 techniques targeting ATAT1, which encodes α-tubulin N-acetyltransferase (αTAT1), resulted in the upregulation of ER stress markers, changes in ER morphology, and enhanced tunicamycin-induced UPR signaling in cancer cells." (PMID 34199510, 2021). "Interestingly, KEGG pathway analysis of 3145 DEGs whose expression levels were lower in ATAT1 KO cells than that in WT cells showed that “Pathways in cancer” was also the most enriched pathway." (PMID 34199510, 2021). "In addition, the disruption of acetyl-α-tubulin by αTAT1 KO significantly reduced cancer progression in vitro and in vivo." (PMID 32917017, 2020). "A recent study on cancer cells showed that an efficient ATAT1 downregulation could impair actin architecture and induce mitotic catastrophe in cells through mechanisms partly independent of acetyl-tubulin." (PMID 27322556, 2016). "Further investigations are needed to better clarify the pathological role of ATAT1 in cell transformation and cancer progression, in which the identification of novel targets and pathways regulated by ATAT1 might represent an important advance toward a more personalized treatment of human tumours." (PMID 38652325, 2024). "Since α-tubulin acetylation levels are dependent on αTAT1/HDAC6 activities, studies have been made to establish how changes in the activity of these enzymes affect cancer cells, namely, their ability to migrate and metastasize." (PMID 37106761, 2023). "However, the role of αTAT1 in the regulation of ER stress in cancer cells is presently unknown." (PMID 34199510, 2021).
cancer (continued). "Nevertheless, the importance of non-enzymatic activities in other ATAT1-related functions, including cell migration and non-axonal intracellular transport, as well as in non-neuronal diseases such as cancer, are still to be clarified." (PMID 38652325, 2024). "The lysine acetylation regulators with CNV amplification showed significantly higher expression in cancer cells when compared to normal cells (e.g. KAT2A and ATAT1), while the regulators with CNV deletion showed significantly lower expression (e.g. SIRT6 and SIRT7)." (PMID 34136387, 2021).
tumor (6 papers, 2018 to 2024). "Subsequently, xenograft experiments also showed that αTAT1 deficiency in MDA-MB-231 cells markedly interrupted tumor growth." (PMID 32917017, 2020). "In our study, immunohistochemical staining revealed that both acetylated α-tubulin and αTAT1 expressions were observed in tumor cells showing reverse polarity in invasive fronts." (PMID 34508164, 2022). "In the distribution analyses, both acetylated α-tubulin and αTAT1 expressions were observed in the tumor cells mainly at the tip of the budding region and the invasive front." (PMID 34508164, 2022). "In our specimens, both acetylated α-tubulin and αTAT1 expressions were observed in the tumor cells mainly at the tip of the intramural growth of the cystic lesion and mural nests." (PMID 34508164, 2022). "Furthermore, co-expression of acetylated α-tubulin and αTAT1 in the cytoplasm of tumor cells was apparent especially at the tip of the invasive front." (PMID 34508164, 2022). "Very recently, it has been shown that p27, a tumor suppressor which promotes autophagy in response to glucose starvation, stimulates MT acetylation by binding to and stabilizing ATAT1, to allow the delivery of autophagosomes in the proximity of the centrosome for efficient fusion with lysosomes." (PMID 35275978, 2022). "Based on the result that the co-expression of acetylated α-tubulin and αTAT1 immunoreaction was seen in the tumor cells especially at the tip of the invasive front of AB, we hypothesized that αTAT1 and tubulin acetylation might be significantly related to the tumor cell migration or invasion in AB." (PMID 34508164, 2022). "As reduced tubulin acetylation and increased migratory behavior are hallmarks of epithelial-to-mesenchymal transition (EMT), in tumor formation as well as in wound healing, repression or silencing of Atat1 might be considered as being essentially involved in the transformation process." (PMID 33672816, 2021). "As the transition of epithelial cells into mesenchymal cells (EMT) in both tumor formation and wound healing is characterized by an increased cell migration as well as reduced tubulin acetylation, repression or silencing of Atat1 might be crucially involved in the transition process." (PMID 33672816, 2021).
infection (5 papers, 2016 to 2025). The state of being infected such as from the introduction of a foreign agent such as serum, vaccine, antigenic substance or organism. "In both 293T cells and in adult DRG cultured neurons, infection with αTAT1 resulted in an increased ratio of acetylated alpha-tubulin." (PMID 28505206, 2017). "Rather, the modest increase in infection observed when this response was inhibited by αTAT1 KO suggests that this response may be antiviral in nature, despite it being unnecessary for TRIM69 restriction." (PMID 39804091, 2025). "This notion is highly supported by our findings that αTAT1 downregulation is both temporally and spatially identical to α-tubulin acetylation changes downstream of MAG or CSPGs treatment, and that αTAT1 reconstitution by lentiviral-αTAT1 infection can overcome neurite growth inhibition." (PMID 29497702, 2018). "Taken together, our data showed that SEPT2 promotes the acetylation of HSPA5 by recruiting the acetylase ATAT1 and that acetylated HSPA5 is critical for controllable M1-like activation and the inflammatory response during infection." (PMID 37978190, 2023). "On the other hand, since the Western blots showed αTAT1-D157N infection did not increase overall acetylated tubulin, this suggests that αTAT1 may induce increased axonal growth independently of catalytic activity, in vitro." (PMID 28505206, 2017).
neurodegenerative disease (1 paper, 2024). A disorder of the central nervous system characterized by gradual and progressive loss of neural tissue and neurologic function. "In line with this, increasing evidence demonstrates the role of ATAT1 function in some neurodegenerative diseases." (PMID 38652325, 2024). "Structural/signalling ATAT1 activities appear to be relevant during neuron development and are likely to be important in neuronal aging and neurodegenerative diseases." (PMID 38652325, 2024).
ATAT1 also shares sentences with these, for which no sentence is quoted: cardiac disease (2 papers); Alzheimer disease (1); ameloblastoma (1); cardiomyopathy (1); depression (1); hematoma (1); male infertility (1); neurological disorders (1); pulmonary fibrosis (1); Stroke (1).